UACA (uveal autoantigen with coiled-coil domains and ankyrin repeats)
Description:
Regulates APAF1 expression and plays an important role in the regulation of stress-induced apoptosis. Promotes apoptosis by regulating three pathways, apoptosome up-regulation, LGALS3/galectin-3 down-regulation and NF-kappa-B inactivation. Regulates the redistribution of APAF1 into the nucleus after proapoptotic stress. Down-regulates the expression of LGALS3 by inhibiting NFKB1 (By similarity). Modulates isoactin dynamics to regulate the morphological alterations required for cell growth and motility. Interaction with ARF6 may modulate cell shape and motility after injury. May be involved in multiple neurite formation (By similarity).
Synonyms: KIAA1561; FLJ10128; NUCLING
Tractability: PROTAC: UniProt records ubiquitination sites on it; ubiquitination databases record sites on it; its protein half-life has been measured.
Gene: Protein-coding gene on chromosome 15 (70,654,554 to 70,763,564, reverse strand). Ensembl gene ENSG00000137831.
Subcellular location: Nucleus; Cytoplasm; Cytoplasm, cytoskeleton
Subcellular location (Human Protein Atlas): Nucleoplasm; Cytosol
Pathways (Reactome):
Programmed Cell Death: Regulation of the apoptosome activity
Signal Transduction: RHOH GTPase cycle
Gene Ontology:
Molecular function: protein binding; actin binding
Biological process: intrinsic apoptotic signaling pathway in response to DNA damage; intrinsic apoptotic signaling pathway in response to oxidative stress; negative regulation of inflammatory response; negative regulation of non-canonical NF-kappaB signal transduction
Cellular component: cytosol; extracellular exosome; nucleoplasm; extracellular region; nucleus; cytoplasm; cytoskeleton
Genetic constraint (gnomAD): Loss-of-function variants: 85 observed, 122.17 expected, observed/expected ratio (o/e) 0.7, 90% interval 0.58 to 0.83. The upper end of that interval is the gene's LOEUF score, 0.83, which puts it in group 3 of 6, group 1 being the genes least tolerant of losing a copy. Missense variants: 1,399 observed, 1,471.1 expected, observed/expected ratio (o/e) 0.95, 90% interval 0.91 to 0.99. Synonymous variants: 492 observed, 528.2 expected, observed/expected ratio (o/e) 0.93, 90% interval 0.86 to 1.
Homologues: Orthologues: chimpanzee UACA (99% identical), macaque UACA (98% identical), pig UACA (88% identical), dog UACA (87% identical), guinea pig UACA (86% identical), rabbit UACA (81% identical), rat Uaca (80% identical), mouse Uaca (79% identical), tropical clawed frog uaca (43% identical), zebrafish uacab (43% identical). Paralogues in human: ANKRD24 (19% identical), ASB2 (9% identical).
Diseases named in the same sentence as UACA in open-access papers:
UACA is named in the same sentence as 20 diseases in open-access papers, as found by Europe PMC text mining. Sharing a sentence is not in itself a finding about the gene and the disease. The quoted sentences say what the papers report.
hepatocellular carcinoma (3 papers, 2022 to 2024). A malignant tumor that arises from hepatocytes. "UACA is a proapoptotic protein that regulates NF-κB signaling, the expression of which is high in various cancers, including hepatocellular carcinoma." (PMID 36362037, 2022). "And cell proliferation and invasion of hepatocellular carcinoma cells can be inhibited by knockdown UACA." (PMID 35507853, 2022). "UACA is upregulated in hepatocellular carcinoma and promotes cell proliferation and invasion." (PMID 39744132, 2024).
breast tumor (2 papers, 2022 to 2025). "In addition, our finding suggests that patients carrying the germline risk alleles likely have higher UACA expression in both normal cells and breast tumor cells." (PMID 35322040, 2022). "We identified 34 differentially expressed genes in metastatic breast tumors, with CCDC6, PKIA, UACA, and PFKP significantly upregulated (p < 0.05)." (PMID 40821334, 2025).
lung adenocarcinoma (2 papers, 2020 to 2021). A carcinoma that arises from the lung and is characterized by the presence of malignant glandular epithelial cells. "Similarly, significantly higher expression of UACA was reported in lung adenocarcinoma and squamous cell carcinoma as compared to normal lung specimens." (PMID 34637398, 2021). "UACA was first identified as an autoantigen in panuveitis patients and later studies showed that UACA expression was higher in lung adenocarcinoma and squamous cell carcinoma, independent of tumor grade 21." (PMID 33294438, 2020).
non-small cell lung carcinoma (2 papers, 2013 to 2022). A group of at least three distinct histological types of lung cancer, including non-small cell squamous cell carcinoma, adenocarcinoma, and large cell carcinoma. "In addition, UACA gene expression has been shown to be down-regulated in non-small cell lung carcinoma (MIM 211980)." (PMID 24146633, 2013).
prostate carcinoma (2 papers, 2020 to 2021). A carcinoma that arises from epithelial cells of the prostate gland. "A recent study reported that the urine level of UACA was higher in prostate cancer patients and UACA could be a biomarker for prostate cancer." (PMID 33294438, 2020).
breast carcinoma (1 paper, 2022). "Because Par-4 has been reported to play an important role in breast cancer recurrence, we then evaluated the impact of UACA locus on recurrence and progression-free survival (PFS), which includes both recurrence and death, among patients treated with anti-HER2 or doxorubicin chemotherapies." (PMID 35322040, 2022). "Our study identified the UACA locus as a genetic predictor of patient outcome following treatment with anthracyclines and/or anti-HER2 therapy, which may have clinical utility in formulating appropriate treatment strategies for breast cancer patients based on their genetic makeup." (PMID 35322040, 2022).
gestational diabetes mellitus (1 paper, 2021). "A study of the Danish National Birth Cohort (608 cases vs 626 control) identified the UACA gene at the cg12157761 associated with the offspring of women with gestational diabetes mellitus." (PMID 33980183, 2021).
ovarian carcinoma (1 paper, 2022). A malignant neoplasm originating from the surface ovarian epithelium. "Again, however, the way in which the reduction in HGF and UACA correlate with the cisplatin resistance of ovarian cancer needs further investigation." (PMID 35008958, 2022).
pancreatic cancer (1 paper, 2021). "In the present study, MA inhibited the expression of UACA and is suggested to suppress pancreatic cancer cells by down-regulating the UACA gene." (PMID 34637398, 2021). "Mechanistically, MA exerts an anti-pancreatic cancer effect by suppressing the expression of key genes, including UACA and AK4." (PMID 34637398, 2021). "Intriguingly, overexpression of UACA abolished the pancreatic antitumor activity of MA, providing evidence that MA exerts anti-pancreatic tumor activity by targeting UACA." (PMID 34637398, 2021). "Wound healing experiments further confirmed that overexpression of UACA or AK4 does not influence the migration ability of pancreatic cancer cells." (PMID 34637398, 2021). "Evidence from our laboratory indicates that UACA overexpression does not affect the proliferation and migration ability of pancreatic cancer cells." (PMID 34637398, 2021). "As far as we know, the role of UACA in pancreatic cancer has not been reported." (PMID 34637398, 2021).
pancreatitis (1 paper, 2021). Inflammation of the pancreas. "UACA was originally identified as a novel autoantigen in patients with pancreatitis, and further evidence demonstrated a higher incidence of IgG anti-UACA antibodies in Vogt-Koyanagi-Harada (VKH) patients than that in healthy controls." (PMID 34637398, 2021).
SAPHO syndrome (1 paper, 2021). SAPHO syndrome (acronym for Synovitis, Acne, Pustulosis, Hyperostosis and Osteitis) is an auto-inflammatory disease, mainly characterized by the association of neutrophilic cutaneous involvement and chronic osteomyelitis. "Through differential analysis of the protein chip, two autoantibodies, against Sp17 and UACA, were identified only in the sera from patients with SAPHO syndrome and not in sera from HCs." (PMID 33392854, 2021).
cancer (8 papers, 2013 to 2023). A tumor composed of atypical neoplastic, often pleomorphic cells that invade other tissues. "Taken together, the loss of UACA in cancer cells might result in altered activation of apoptotic pathways, ultimately promoting genesis of CRC." (PMID 24146633, 2013). "As after cancer diagnosis, patients can progress to death through two mutually exclusive courses: death after recurrence versus death without recurrence, we used a competing risk model to investigate how the UACA locus may affect these two courses." (PMID 35322040, 2022). "For proteomics verification, 2 genes (UACA and AK4) identified to be closely related to cancer, according to the results of association analysis, were subjected to western blot." (PMID 34637398, 2021). "In this view, inhibition of UACA expression can enhance the sensitivity of cancer cells to apoptosis." (PMID 34637398, 2021). "There are 4 genes (UACA, PTTG1IP, PIGR, CD81) of this GO term may interacted with ACTR2, EIF6 and hsa-miR-139-5p at the same time, and they play an important role in cancer associated pathway: apoptotic process (UACA, PTTG1IP) and immunity (PIGR, CD81)." (PMID 37365497, 2023). "UACA is an oncogene known to induce apoptosis resistance in cancer." (PMID 35615145, 2022). "Moreover, the uveal autoantigen with coiled-coil domains and ankyrin repeats (UACA/Nucling) is upregulated in various cancers types." (PMID 35008958, 2022). "The following genes displayed LOH in at least one cancer: UACA, TWSG1, PSPH, and ZNF490." (PMID 24146633, 2013). "By contrast, NF-κB activity and UACA expression were not inhibited by CQ in cancer cells, and this blockade presumably prevented Par-4 secretion from those cells in response to CQ." (PMID 28076793, 2017).
tumor (8 papers, 2014 to 2025). "Higher UACA expression in normal cells results in lower extracellular Par-4 levels, leading to reduced tumor apoptosis and worse prognosis." (PMID 39744132, 2024). "Higher UACA expression in tumor cells results in a reduced sensitivity to therapeutic agents that rely on Par-4 induced apoptosis and hence worse prognosis." (PMID 35322040, 2022). "Therefore, higher UACA expression in normal cells results in lower extracellular Par-4 level, which again leads to reduced tumor apoptosis and worse prognosis." (PMID 35322040, 2022). "On the basis of previous research, two genes, UACA and AK4 that may be associated with the anti-tumor mechanism of MA, were screened and discussed." (PMID 34637398, 2021). "Genes including UACA and CFLAR exhibited elevated expression in epithelial cells, macrophages and endothelial cells, suggesting involvement in tumor-immune crosstalk." (PMID 41293156, 2025). "CAFs-Exo was found to be involved in tumor immune regulation through hsa-miR-139-5p, ACTR2 and EIF6, while PIGR, CD81, UACA and PTTG1IP may be potentially effective targets for the treatment of OSCC in the future." (PMID 37365497, 2023).
UACA also shares sentences with these, for which no sentence is quoted: squamous cell carcinoma (2 papers); airway allergy (1); Allergy (1); Alzheimer disease (1); diabetes mellitus (1); panuveitis (1); small cell lung carcinoma (1).